ZDHHC2 (zDHHC palmitoyltransferase 2)
Diseases named in the same sentence as ZDHHC2 in open-access papers (continued):
Sharing a sentence is not in itself a finding about the gene and the disease.
gastric cancer (1 paper, 2013). A primary or metastatic malignant neoplasm involving the stomach. "In the present study, reduced ZDHHC2 expression in gastric cancer was found to be associated significantly with lymph node metastasis (p<0.001), suggesting that ZDHHC2 might play an important role in gastric cancer metastasis." (PMID 23457560, 2013). "Weak ZDHHC2 expression was observed in the cytoplasm of gastric cancer tissues, while strong ZDHHC2 expression was observed predominantly in the cytoplasm of adjacent normal tissues." (PMID 23457560, 2013). "In early stage (stage I and II) gastric cancer, the patients with the low levels of ZDHHC2 expression (n = 60) had a poorer prognosis than the patients with high levels of ZDHHC2 expression (n = 105) (p = 0.001)." (PMID 23457560, 2013). "Correlation between ZDHHC2 expression and clinicopathological variables of 472 gastric cancer cases." (PMID 23457560, 2013). "Meanwhile, in late stage (stage III and IV) gastric cancer, the patients with the low levels of ZDHHC2 expression (n = 151) also had a poorer prognosis than the patients with high levels of ZDHHC2 expression (n = 156) (p = 0.001)." (PMID 23457560, 2013). "ZDHHC2 expression had a significant, independent predictive value for survival of gastric cancer patients (p = 0.001)." (PMID 23457560, 2013). "ZDHHC2 expression was reduced in 68.9% (31/45) of gastric cancer patients as shown by immuohistochemistry, compared with paired adjacent normal tissues." (PMID 23457560, 2013). "ZDHHC2 expression was reduced in 66.7% (30/45) of gastric cancer patients, compared with paired adjacent normal tissues." (PMID 23457560, 2013). "Multivariate Cox regression analysis indicated that ZDHHC2 expression had a significant, independent predictive value for survival of gastric cancer patients (HR = 0.627, p = 0.001)." (PMID 23457560, 2013). "Moreover, immunohistochemistry was performed to detect ZDHHC2 expression in 45 cases of gastric cancer tissues and paired adjacent normal tissues." (PMID 23457560, 2013). "To avoid the uncertainty of ZDHHC2 score around the median, we also compared the five-year OS rate of the gastric cancer patients with lowest ZDHHC2 expression (composite score less than 4, n = 74) with those with highest ZDHHC2 expression (composite score more than 8, n = 128)." (PMID 23457560, 2013). "Furthermore, reduced ZDHHC2 expression is a significant, independent predictive factor for survival of gastric cancer patients." (PMID 23457560, 2013). "Furthermore, our results indicated that ZDHHC2 expression had a significant, independent predictive value for survival of gastric cancer patients (p = 0.001)." (PMID 23457560, 2013). "Furthermore, the average relative expression of ZDHHC2 in all 45 cases of gastric cancer tissues is lower than that of ZDHHC2 in adjacent normal tissues." (PMID 23457560, 2013). "Moreover, the mean staining score of ZDHHC2 in all 45 cases of gastric cancer tissues is lower than that of ZDHHC2 in adjacent normal tissues." (PMID 23457560, 2013). "Hence, the substrate and function of ZDHHC2 in gastric cancer deserve for further study." (PMID 23457560, 2013). "Compared to the normal tissues, ZDHHC2 expression was almost negative in patients with poorly differentiated carcinoma (G3), while weak ZDHHC2 expression (G2) and strong ZDHHC2 expression (G1) were found in moderately differentiated gastric cancer and well-differentiated gastric cancer respectively." (PMID 23457560, 2013).
gastric tumor (1 paper, 2013). "Here we provided evidence that ZDHHC2 expression was significantly reduced in gastric tumor tissues, compared to the adjacent normal tissues." (PMID 23457560, 2013). "Compared to the adjacent normal tissues, ZDHHC2 expression was significantly reduced in gastric tumor tissues as shown by qRT-PCR and immunostaining." (PMID 23457560, 2013).
liver cancer (1 paper, 2023). An epithelial or non-epithelial malignant neoplasm that arises from the liver. "Overexpression of ZDHHC2 can inhibit the migration and invasion of liver cancer cells." (PMID 36774350, 2023).
nasopharyngeal carcinoma (1 paper, 2016). A carcinoma arising from the nasopharyngeal epithelium. "In nasopharyngeal carcinoma, the miR-155 inhibitor could inhibit cell migration by targeting ZDHHC2." (PMID 26967247, 2016).
Obesity (1 paper, 2025). Accumulation of substantial excess body fat. "GWAS have identified four of these (INPP5A, ZDHHC2, IQCF6, and PRKCH) to be associated with BMI or obesity." (PMID 40892850, 2025).
Parkinson disease (1 paper, 2022). A progressive degenerative disorder of the central nervous system characterized by loss of dopamine producing neurons in the substantia nigra and the presence of Lewy bodies in the substantia nigra and locus coeruleus. "It was also suggested that the presence of zDHHC2 protects dopaminergic neurons from death during the course of Parkinson’s disease." (PMID 36087837, 2022).
prostate tumors (1 paper, 2020). "DHHC PATs can predominantly exhibit either oncogenic or tumor suppressor function in specific cancers; e.g., ZDHHC2 as a tumor suppressor in breast, lung, and prostate tumors 28-30." (PMID 31938047, 2020).
tumor (13 papers, 2013 to 2026). "In accord with the correlation of LOH of ZDHHC2 and clinical parameters, lower expression of ZDHHC2 was associated with the tumor size and the presence of PVTT." (PMID 24995331, 2014). "What is more, reduction of ZDHHC2 expression was associated significantly with lauren classification (p<0.001), tumor size (p = 0.026), TNM staging (p = 0.012) and location (p = 0.006)." (PMID 23457560, 2013). "ZDHHC2 functions as a tumor suppressor, and its reduced expression predicts poor prognosis in gastric adenocarcinoma patients and is associated with lymph node metastasis." (PMID 40814339, 2025). "We found that the LOH on ZDHHC2 was associated with early metastatic recurrence of HCC following LT and was correlated with tumor size and portal vein tumor thrombi (PVTT)." (PMID 24995331, 2014). "Further study provides the evidence that ZDHHC2 has important role as a tumor suppressor in metastasis and recurrence of HCC." (PMID 24995331, 2014). "To investigate the expression of ZDHHC2 in tumor tissues and peritumor tissues from HCC samples, we conducted qRT-PCR in cohort 2 of 55 HCC samples and IHC in cohort 3 of 23 HCC samples." (PMID 24995331, 2014). "LOH on ZDHHC2 was associated with early metastatic recurrence of HCC following liver transplantation and was correlated with tumor size and portal vein tumor thrombi." (PMID 24995331, 2014). "We found that mRNA level of ZDHHC2 expression is significantly lower in tumor tissues than peritumor tissues from the same patients (P = 0.003)." (PMID 24995331, 2014). "Zinc finger, DHHC-type containing 2 (ZDHHC2), originally named as reduced expression associated with metastasis protein (REAM), has been proposed as a putative tumor/metastasis suppressor gene and is often aberrantly decreased in human cancers." (PMID 23457560, 2013). "The first substrate of ZDHHC2 related to its tumor/metastasis suppressor function is CKAP4/p63, which was identified as a cell surface receptor for antiproliferative factor (APF)." (PMID 23457560, 2013). "The second substrate of ZDHHC2 related to its putative tumor/metastasis suppressor is tetraspanins CD9 and CD151." (PMID 23457560, 2013). "ZDHHC2 knockout significantly limited tumor growth and enhanced the enzalutamide sensitivity." (PMID 41126755, 2026). "Furthermore, by multiplying the values of staining intensity and relative abundance of positive cells, we found that the mean staining score of ZDHHC2 in tumor tissues is significantly lower than those in peritumor tissues (P = 0.015)." (PMID 24995331, 2014). "In addition, our data showed that LOH status of ZDHHC2 was correlated with some clinicopathological parameters, including tumor size and PVTT." (PMID 24995331, 2014). "This discovery provides one plausible mechanism by which ZDHHC2 may function as a tumor suppressor." (PMID 23457560, 2013). "Which substrate could make ZDHHC2 function as putative tumor/metastasis suppressor?" (PMID 23457560, 2013). "ZDHHC2 overexpression has been shown to inhibit the proliferation, migration, and invasion of HCC cells in vitro, highlighting its role as a tumor suppressor in HCC metastasis and recurrence." (PMID 40681504, 2025). "zDHHC2 expression was decreased in HCC samples and cell lines while zDHHC2 overexpression inhibited proliferation, migration, and invasion in HCC cell lines, suggesting that zDHHC2 acts as tumor suppressor." (PMID 39429488, 2024). "Zinc finger, DHHC-type containing 2 (ZDHHC2), proposed as a putative tumour/metastasis suppressor gene and was often aberrantly decreased in human cancers." (PMID 35057823, 2022). "We analyzed the correlation between ZDHHC2 mRNA expression and clinical parameters including age, preoperative serum AFP level, tumor number, tumor size, PVTT, and histopathologic grading." (PMID 24995331, 2014).
tumor (continued). "Taken together, significant associations were found between HCC recurrence and the following variables: LOH on ZDHHC2, preoperative AFP level >400 ng/mL, tumor size >5 cm, and presence of PVTT." (PMID 24995331, 2014). "Research has demonstrated that ZDHHC2 regulates antiproliferative signaling by mediating the palmitoylation of CKAP4, indicating that ZDHHC2 may function as a tumor suppressor." (PMID 40681504, 2025). "ZDHHC17 and ZDHHC20 may act as oncoproteins 43, 44, but ZDHHC2 and ZDHHC13 can act as tumor suppressors 45-47." (PMID 32863941, 2020). "Multivariate analyses revealed that LOH on ZDHHC2 could predict the risk of HCC early recurrence together with AFP level, tumor size, and PVTT but was not an independent prognostic factor." (PMID 24995331, 2014). "However, inhibition of ZDHHC2, ZDHHC3, and ZDHHC7, which are responsible for palmitoylating Foxp3, might reduce the nuclear localization and stability of Foxp3 in both peripheral lymphoid tissues (e.g., spleen, lymph nodes) and tumor-infiltrating Tregs." (PMID 40814339, 2025).
cancer (10 papers, 2013 to 2025). A tumor composed of atypical neoplastic, often pleomorphic cells that invade other tissues. "ZDHHC2 was originally described as REAM (reduced expression in metastasis), because its silence was associated with increased metastatic potential of cancer cells." (PMID 24995331, 2014). "The discovery that CKAP4/p63, the receptor for APF, is a substrate of ZDHHC2, provides an important link between the proliferative properties of many types of cancer cells and the reduced expression or mutation of ZDHHC2." (PMID 23457560, 2013). "As a member of DHHC-palmitoyl transferases, Zdhhc2 has been mainly studied in the field of cancer and neuroscience." (PMID 32587588, 2020). "There is significant difference in ZDHHC2 mRNA expression between cancer tissues and adjacent normal tissues (p = 0.03)." (PMID 23457560, 2013). "There is significant difference in ZDHHC2 protein expression between cancer tissues and adjacent normal tissues (p = 0.00)." (PMID 23457560, 2013).
neurodegenerative disease (2 papers, 2022 to 2025). A disorder of the central nervous system characterized by gradual and progressive loss of neural tissue and neurologic function. "Along with this, the pharmacological modulation of zDHHC2 is studied in restoring synaptic functions in neurodegenerative diseases." (PMID 40831763, 2025). "These mechanistic disruptions directly link zDHHC2/3 dysfunction to impaired excitatory/inhibitory synaptic balance, a key feature of neurodegenerative diseases such as AD and PD, where synaptic dysfunction precedes neuronal loss." (PMID 40831763, 2025). "Similarly, PSD-95 is catalyzed by zDHHC2 localization to dendritic vesicles, enhancing zDHHC2 activity may strengthen the synaptic plasticity, which is often compromised in neurodegenerative diseases." (PMID 40831763, 2025). "From our data, we also speculate that the dissociation of zDHHC2 from the PSD may lead to reduced clustering of PSD95 at the synapse, though the precise role of protein palmitoylation in neurodegenerative disease remains to be determined." (PMID 35305541, 2022).
ZDHHC2 also shares sentences with these, for which no sentence is quoted: breast carcinoma (5 papers); acute myeloid leukemia (2); malaria (2); metastatic cancers (2); non-small cell lung carcinoma (2); bladder cancers (1); cerebrovascular disease (1); clear cell renal cell carcinoma (1); colon cancer (1); eosinophilia (1); interstitial cystitis (1); parasitemia (1); skin inflammatory diseases (1); testicular germ cell tumor (1); X-linked intellectual disability (1).